SPTBN5 (spectrin beta, non-erythrocytic 5)
Synonyms: BSPECV; HUBSPECV; HUSPECV
Tractability: Antibody: its Gene Ontology location is reachable by antibodies, with medium confidence.
Gene: Protein-coding gene on chromosome 15 (41,848,146 to 41,894,053, reverse strand). Ensembl gene ENSG00000137877.
Subcellular location: Cytoplasm, cytoskeleton
Pathways (Reactome):
Developmental Biology: Interaction between L1 and Ankyrins; NCAM signaling for neurite out-growth
Signal Transduction: RAF/MAP kinase cascade
Vesicle-mediated transport: COPI-mediated anterograde transport
Gene Ontology:
Molecular function: dynactin binding; dynein intermediate chain binding; identical protein binding; kinesin binding; myosin tail binding; spectrin binding; actin binding; actin filament binding; cytoskeletal protein binding; opsin binding
Biological process: Golgi organization; lysosomal transport; actin cytoskeleton organization
Cellular component: cytoplasm; photoreceptor connecting cilium; photoreceptor disc membrane; cell junction; cortical actin cytoskeleton; cytosol; membrane; plasma membrane; spectrin; apical cortex; cortical cytoskeleton; cytoskeleton; microtubule associated complex; organelle; plasma membrane bounded cell projection
Genetic constraint (gnomAD): Loss-of-function variants: 510 observed, 403.86 expected, observed/expected ratio (o/e) 1.26, 90% interval 1.17 to 1.36. The synonymous counts are far from expectation, so gnomAD's model fits this gene poorly and the ratio says little. Missense variants: 5,058 observed, 4,279.9 expected, observed/expected ratio (o/e) 1.18, 90% interval 1.15 to 1.21. Synonymous variants: 2,168 observed, 1,811.9 expected, observed/expected ratio (o/e) 1.2, 90% interval 1.15 to 1.24.
Homologues: Orthologues: chimpanzee SPTBN5 (98% identical), macaque SPTBN5 (93% identical), dog SPTBN5 (69% identical), pig SPTBN5 (67% identical), rabbit SPTBN5 (65% identical), mouse Sptbn5 (63% identical), rat Sptbn5 (61% identical), zebrafish sptbn5 (37% identical), Drosophila melanogaster kst (32% identical), Caenorhabditis elegans sma-1 (29% identical). Paralogues in human: SPTAN1 (17% identical), SPTBN2 (16% identical), SPTBN4 (16% identical), SPTBN1 (16% identical), SPTB (15% identical), SPTA1 (15% identical), MACF1 (15% identical), DST (15% identical), SYNE1 (14% identical), SYNE2 (13% identical), PLEC (12% identical), UTRN (10% identical), and 24 more.
Diseases named in the same sentence as SPTBN5 in open-access papers:
SPTBN5 is named in the same sentence as 20 diseases in open-access papers, as found by Europe PMC text mining. Sharing a sentence is not in itself a finding about the gene and the disease. The quoted sentences say what the papers report.
developmental delay (4 papers, 2022 to 2023). "In this study, we report, for the first time, four different families of SPTBN5 deficiency with features such as ID, developmental delay, seizures, aggressive behavior, variable dysmorphic features, and limb malformations." (PMID 35782384, 2022). "A variant of SPTBN5 leads to intellectual disability, seizures, and developmental delays in humans." (PMID 37993775, 2023). "We read with great interest the newest paper in this field, which implicates four different heterozygous de novo variants in SPTBN5 (His89Pro, Tyr311*, Asn2937Tyr, Glu3262Lys) as the disease cause in patients with a combination of intellectual disability, developmental delay and seizures." (PMID 36117916, 2022).
Intellectual disability (4 papers, 2022 to 2023). "The SPTBN5-associated clinical traits in our patients include intellectual disability (mild to severe), aggressive tendencies, accompanied by variable features such as craniofacial and physical dysmorphisms, autistic behavior, and gastroesophageal reflux." (PMID 35782384, 2022).
glioma (2 papers, 2024 to 2025). A benign or malignant brain and spinal cord tumor that arises from glial cells (astrocytes, oligodendrocytes, ependymal cells). "Finally, functional experiments were performed to evaluate the roles of risk genes in the cell viability of glioma cells, which demonstrated that silencing BGN, SDC1, SERPINA1, TUBA1C, C1GALT1C1L and SPTBN5 could inhibit the growth and viability of glioma cells." (PMID 38396140, 2024). "Moreover, functional experiments were performed to evaluate the roles of risk genes in the cell viability and cell number of glioma U87 and U251 cells, which demonstrated that silencing BGN, SDC1, SERPINA1, TUBA1C, C1GALT1C1L and SPTBN5 could inhibit the growth and viability of glioma cells." (PMID 38396140, 2024).
brain malformation (1 paper, 2022). "Additional functional evidence is needed to clarify how the SPTBN5 haploinsufficiency affects brain malformation." (PMID 35782384, 2022).
depression (1 paper, 2024). "The roles of Ciart, Rorb and Sptbn5 were previously indicated in various neurological disorders, including seizures, Parkinson’s disease and depression." (PMID 38439070, 2024).
epilepsy (1 paper, 2024). A brain disorder characterized by episodes of abnormally increased neuronal discharge resulting in transient episodes of sensory or motor neurological dysfunction, or psychic dysfunction. "Similarly, in another study, a missense SPTBN5 variant was detected in a Pakistani family with early-onset epilepsy, behavioral impairments, and gastroesophageal reflux." (PMID 38783254, 2024).
metabolic syndrome (1 paper, 2017). A cluster of metabolic risk factors for CARDIOVASCULAR DISEASES and TYPE 2 DIABETES MELLITUS. "SNPs in the SPTBN5 gene have been associated with stroke incidence in a Japanese population, but only in patients with metabolic syndromes." (PMID 29297313, 2017).
retinitis pigmentosa (1 paper, 2015). Retinitis pigmentosa (RP) is an inherited retinal dystrophy leading to progressive loss of the photoreceptors and retinal pigment epithelium and resulting in blindness usually after several decades. "Mutations in SPTBN5 and RPGRIP1L cause retinitis pigmentosa." (PMID 26083354, 2015).
neurological disorders (2 papers, 2022 to 2024). "Variants in the spectrin genes SPTAN1, SPTBN1, SPTBN2, and SPTBN4 have been associated with neurological disorders; however, SPTBN5 gene-variants have not been associated with any human disorder." (PMID 35782384, 2022). "In addition, mutations in various members of the spectrin gene family are associated with erythroid cell disorders (SPTA1, SPTB) and neurological disorders (SPTAN1, SPTBN1, SPTBN2, and SPTBN4); however, no human genotype-phenotype correlation has been established for SPTBN5 to date." (PMID 35782384, 2022).
tumor (1 paper, 2023). "We found that most genes with hazard ratio > 1 (GPRASP1, APLP1, ALPK3, SPTBN5, PCDHB14, LZTS3 and RGL2) have a higher expression in tumor tissues than normal tissues except LINGO1 and LZTS1." (PMID 37237274, 2023). "Protein level of tumor promoting genes (GPRASP1, APLP1, ALPK3, SPTBN5, PCDHB14, LZTS3, RGL2) were higher in tumor tissues." (PMID 37237274, 2023).
SPTBN5 also shares sentences with these, for which no sentence is quoted: breast carcinoma (1 paper); cancer (1); Cerebral atrophy (1); gastroesophageal reflux (1); infection (1); mastitis (1); melanoma (1); Parkinson disease (1); Seizure (1); Stroke (1).